GSDME (gasdermin E)
Diseases named in the same sentence as GSDME in open-access papers (continued):
Sharing a sentence is not in itself a finding about the gene and the disease.
cancer (continued). "In this review, we describe the molecular process of GSDME-mediated PCD and summarize therapeutic advances associated with GSDME and cancer suppression." (PMID 34335940, 2021). "Several anti-cancer agents promote the cleavage of GSDME into N-GSDME, thereby promoting the death of cancer cells." (PMID 34867412, 2021). "In general, GSDME is highly expressed in normal cells, whereas its expression is varied in different types of cancer." (PMID 33634141, 2021). "It has been proven that etoposide, paclitaxel, and cisplatin can induce pyroptosis in cancer cells with high expression of gasdermin E (GSDME)." (PMID 34616734, 2021). "Ever since the mechanism of GSDME mediated pyroptosis was revealed, an increasing number of studies have been focused on its role in cancer." (PMID 34820376, 2021). "GSDME is reduced in several cancers, including CRC, through a mechanism that involves methylation of its promoter." (PMID 35111698, 2021). "On the other hand, GSDME expression is silenced in most cancer cells, likely attributed to promoter methylation of the GSDME gene." (PMID 33406603, 2021). "The switch from apoptosis to pyroptosis potentially bypasses antiapoptotic obstacles and overcomes chemoresistance; thus, appropriate induction of GSDME-mediated pyroptosis is a primary issue in cancer treatment." (PMID 34522213, 2021). "The cleavage of GSDME after treatment of cancer with chemotherapy agents provides a cross-talk between the pro-inflammatory process of pyroptosis and the anti-inflammatory process of apoptosis." (PMID 34867412, 2021). "The cancer cells with high expression of GSDME undergo pyroptosis when treated with chemotherapeutic drugs while cells with low or no expression of GSDME undergo apoptosis." (PMID 34381721, 2021). "Pyroptosis is a form of programmed cell death, in which gasdermin E (GSDME) plays an important role in cancer cells, which can be induced by activated caspase-3 on apoptotic stimulation." (PMID 34305590, 2021). "Our first pan-cancer analysis of GSDME not only broadens the understanding of the carcinogenic roles of GSDME but also provides a promising therapeutic strategy for benefiting an increasing number of cancerous patients based on GSDME-induced pyroptosis." (PMID 34381728, 2021). "Accumulating evidence has been documented the unique GSDME protein is involved in a series of biological processes in various cancer types, including ontogeny, homeostasis, and pathological processes." (PMID 34381728, 2021). "Previous studies have extensively documented a molecular machinery involving epigenetic inactivation due to GSDME promoter hypermethylation in a range of human cancers." (PMID 34901025, 2021). "The “Pathological Stage Plot” module of GEPIA was used to analyze the relationship between GSDME expression and the pathological stages of different cancers, including BLCA, ESCA, KICH, KIRC, KIRP, READ, and UCEC (all P value <0.05)." (PMID 34381728, 2021). "Expression of human GSDMB or GSDME sensitized cancer cells to cytotoxic lymphocyte-induced pyroptosis in a granzyme-dependent manner." (PMID 33406603, 2021). "Although the expression and post-translational modification of GSDME in various types of cancer have been examined in several studies, the exact role and underlying molecular mechanisms of these processes remain ambiguous." (PMID 34858408, 2021). "GSDME is highly expressed in most malignant cancers, and obvious relationship exists between GSDME level and survival prognosis of cancer patients." (PMID 34381728, 2021). "The expression of GSDME was observed in some cancers, while it was epigenetically silenced in the majority of cancer cell lines owing to the hypermethylation of its promoter." (PMID 33634141, 2021). "Our study showed that TPL treatment triggered GSDME-mediated pyroptotic cell death in cancer cells through repressing mitochondrial HK-II expression." (PMID 34108030, 2021).
cancer (continued). "As a major factor in pyroptosis, GSDME has recently been shown to be able to convert apoptosis into pyroptosis, thereby notably suppressing cancer cell proliferation and improving the beneficial effects of chemotherapy." (PMID 32863941, 2020). "What’s more, the silence of GSDME in certain cancer cell types is relieved by decitabine, a kind of DNA methyltransferase inhibitor, which leads to the elevated expression of GSDME and the enhanced sensitivity of GSDME-silenced cancer cells to doxorubicin." (PMID 33665167, 2020). "The caspase-3/GSDME signal pathway as a “switch” that can shift the balance between apoptosis and pyroptosis in cancer." (PMID 33133646, 2020). "In fact, the expression of GSDME is commonly inhibited due to DNA methyltransferase in most cancer cells." (PMID 33665167, 2020). "This review will summarize and discuss the potential effects of caspase-3 dependent cell death on cancer and the side effects of chemotherapy in caspase-3-dependent cell death with high expression of GSDME." (PMID 33133646, 2020). "Recently, another gasdermin family member, gasdermin E (GSDME), was reported to induce pyroptosis in various cancer cells." (PMID 32341339, 2020). "In-depth study of the relationships about osteosarcoma and caspase-3 and GSDME are helpful for cancer treatment." (PMID 33133646, 2020). "This article mainly reviews the caspase-3/GSDME signal pathway as a switch between apoptosis and pyroptosis in cancer, to provide new strategies and targets for cancer treatment." (PMID 33133646, 2020). "The third is induced by chemotherapy drugs in cancer cells, where activated caspase-3 induced GSDME cleavage." (PMID 32332857, 2020). "As GSDMD and GSDME are crucial executors of pyroptosis, here we explain the anti-cancer effects of pyroptosis by introducing the role of GSDMD and GSDME." (PMID 33665167, 2020). "As cancer cells express little GSDME, reversal of GSDME silencing can potentially sensitise cancer cells to chemotherapy drugs." (PMID 33033617, 2020). "How to find a balance point to utilize caspase-3/GSDME-mediated pyroptosis for cancer treatment is an open question and needs more further investigaions." (PMID 33133646, 2020). "In cancer cell lines with high GSDME expression, such as SH-SY5Y cells and MeWo cells, scholars identified a caspase-3-cleavable site 267DMPD270 in human GSDME5." (PMID 33133646, 2020). "Study showed that L61H10 exerted the cancer inhibitory effects through arresting the cell cycle in the G2/M phase and mediating the NF-κB modulated apoptosis to GSDME-mediated pyroptosis transformation." (PMID 31616642, 2019). "Soon after these studies, several other studies pointed towards an important role for GSDME in secondary necrosis and its possible pathophysiological and therapeutic implications, especially in cancer." (PMID 31434357, 2019). "Overexpression of GSDME in cancer cells switched caspase-3-mediated apoptosis triggered by tumor necrosis factor (TNF) or chemotherapeutic agents to pyroptosis." (PMID 31492049, 2019). "GSDMD and GSDME are two important pyroptotic substrates, and they also exert other critical roles in the pathogenesis and treatment strategies exploit of cancer." (PMID 31616642, 2019). "Many studies have shown that GSDME is highly expressed in normal tissues but silenced in cancers due to promoter hypermethylation." (PMID 31612107, 2019). "The clinical significance of GSDME-dependent pyroptosis in cancer chemotherapy of CRC still requires further investigation." (PMID 30804337, 2019). "Our analyses highlight that a Gasdermin E methylation biomarker assay, not only has the potential for being a methylation-specific pan-cancer detection marker, but it also possesses the capacity to discriminate between different types of tumors." (PMID 31752152, 2019). "More investigations are required to disclose the precise mechanisms behind GSDMD- and GSDME-mediated pyroptotic pathways, which would provide clues for cancer chemotherapy." (PMID 31492049, 2019).
cancer (continued). "In this study, we demonstrated that GSDME augments the intrinsic apoptotic pathway in cancer cells by forming pores in the mitochondria and releasing critical proapoptotic factors such as Cyt c and HtrA2." (PMID 30976076, 2019). "The divergent roles of GSDME, as a therapeutic inducer in cancer and a potential pathological mediator in neurons, exemplify the “double‐edged sword” nature of pyroptosis executors and underscore the necessity for mechanism‐ and context‐specific therapeutic strategies." (PMID 41574659, 2026). "TUNEL-Cy3 staining also showed that Tc3 could promote apoptosis in a proportion of cancer cells when GSDME was knocked down." (PMID 39816682, 2025). "This discrepancy of results between different studies highlights that the function of GSDME may be highly dependent on the cancer type." (PMID 40544161, 2025). "GSDME cleavage by caspase 3 represents the most common pyroptosis pathway in cancer cells." (PMID 40645933, 2025). "Additionally, natural compounds such as cucurbitacin B and dasatinib have been shown to activate GSDMD or GSDME, resulting in enhanced pyroptotic and apoptotic death of cancer cells, sometimes involving mitochondrial ROS, STAT3, and NF-κB pathways." (PMID 40806716, 2025). "Additionally, biomimetic nanoparticles, such as ZIF-8 coated with cancer cell membranes, enhance oxaliplatin delivery and GSDME-mediated pyroptosis by inducing GSDME upregulation through DNA methyltransferase inhibition." (PMID 41235238, 2025). "A recent study has demonstrated that GSDME is specially cleaved by activated Caspase-3 in response to TNFα plus cycloheximide (CHX) to generate GSDME-NT that is responsible for inducing pyroptosis in cancer cells." (PMID 40103680, 2025). "Additionally, GSDME expression in cancer models generally inhibits cell growth and induces cell death, while various antioncologic treatments have been shown to induce GSDME processing and cell death." (PMID 40783818, 2025). "In cancer cells, caspase-3 is in turn activated and cleaves GSDME to trigger pyroptosis." (PMID 40842867, 2025). "It is expected that this design could increase the cleavage of GSDME by Caspase‐3, thereby enhancing the induction of pyroptosis and activating a stronger cancer immune effect." (PMID 40432601, 2025). "Chemotherapeutic drugs can induce GSDME-mediated pyroptosis and thus may contribute to beneficial responses in a subset of cancer patients." (PMID 40544161, 2025). "The authors also observed that GSDME was silenced in cancer cells but expressed in normal cells." (PMID 40544161, 2025). "5-Fluorouracil 49 induces pyroptosis in various cancer cells through the activation of GSDME." (PMID 39316325, 2025). "Interestingly, recent studies have shown that cisplatin can induce pyroptosis by triggering caspase-3–mediated cleavage of GSDME in cancer cells." (PMID 40890114, 2025). "GSDME is considered a tumor suppressor gene in most cancers due to its low expression." (PMID 39526199, 2024). "Therefore, GSDME-mediated pyroptosis contributes to toxic side effects observed during cancer chemotherapy." (PMID 38987821, 2024). "This further established that GSDMs are primarily involved in the progression of HCC as oncogenes, but the advanced cancer tissues might interfere with the expression of GSDME." (PMID 38434972, 2024). "Interestingly, the caspase-3/GSDME signaling pathway is a “switch” that can shift the balance between apoptosis and pyroptosis in cancer." (PMID 38732000, 2024). "Similarly, analyses by the Ualcan platform showed increased expression of GSDME in cancer tissues compared with normal counterparts and a tumor-grade-dependent increase." (PMID 38732000, 2024). "Therefore, it is believed that, in most cancer cells, GSDME is epigenetically silenced by excessive promoter hypermethylation." (PMID 39526199, 2024). "However, in the majority of cancer cells, including those from the stomach, breast, and colon, GSDME is silenced as a result of promoter DNA hypermethylation." (PMID 38643134, 2024).
cancer (continued). "For example, doxorubicin has been found to activate the caspase-3/gasdermin E (GSDME) pathway, triggering pyroptosis, which may affect the clinical outcome of cancer patients." (PMID 38954046, 2024). "On the other hand, GSDME−/− mice show less injury, indicating that triggering pyroptosis in cancer cells might offer a potential alternative approach for cancer treatment." (PMID 39620145, 2024). "It is suggested that inducing cancer cell-specific pyroptosis by activating GSDME expression may be a potential therapeutic strategy against GC." (PMID 38654314, 2024). "Since GSDME-mediated pyroptosis was identified, studies have focused on its role in cancer." (PMID 39526199, 2024). "Furthermore, the caspase-3 can switch between apoptosis and pyroptosis in cancer through interacting with gasdermin E (GSDME)." (PMID 39075259, 2024). "Our current finding reveals a new regulating mechanism of GSDME expression, which may be a viable target for the intervention of GSDME-dependent inflammatory diseases and cancer therapy." (PMID 38238307, 2024). "However, GSDME is often downregulated or even silenced in cancer cells due to hypermethylation of its promoter 58,59." (PMID 38725862, 2024). "GSDME is a mediator of cancer cell pyroptosis dependent on caspase-3 cleavage." (PMID 39075259, 2024). "Anti-cancer immune responses are primarily executed by GSDME-mediated pyroptosis." (PMID 38238307, 2024). "Reversing the expression level of GSDME in cancer cells may hold the key to leveraging pyroptosis therapy for EC treatment in the coming years." (PMID 37965452, 2023). "Future research in this area may suggest new strategies to better use GSDME-mediated pyroptosis to treat cancer." (PMID 36867605, 2023). "In cancer cells with low GSDME expression, Caspase3 tends to induce apoptosis." (PMID 37415742, 2023). "Additionally, a combination of BIX‐01294 (BIX) and cisplatin shows human cancer cell pyroptosis with cleavage of GSDME and caspase‐3." (PMID 37125240, 2023). "The expression of GSDME suppresses the colony formation and proliferation of cancer cells." (PMID 37085908, 2023). "Furthermore, GSDME in cancer cells is also activated by NK and cytotoxic T cells upon delivery of granzyme B through perforin pores." (PMID 37771587, 2023). "Similarly, oncolytic vesicular stomatitis virus (VSV) induced cancer cell pyroptosis by activating GSDME." (PMID 38283351, 2023). "The mechanism of lobaplation against human CRC cancer is related to GSDME‐dependent pyroptosis, which may have promising in the anticancer clinical application." (PMID 37125240, 2023). "We found that GSDME depletion reduced the proliferation of NSCLC cancer cells in vitro." (PMID 37085908, 2023). "Decitabine could reverse the low expression of GSDME in cancer cells and enhance the sensitivity of cancer cells to chemotherapy medicines." (PMID 38016064, 2023). "GSDME expression is silenced by promoter methylation in different types of cancer." (PMID 37771587, 2023). "In addition, it has been observed that the N-terminal domain of GSDME, after its cleavage mediated by caspase-3, triggers the intrinsic apoptotic pathway of cancer cells." (PMID 37627547, 2023). "Indeed, increased levels of GSDME in cancer cells resulted in a substantial rise in the number of antigen-specific CD8+ T cells and intra-tumoral NK cells." (PMID 36831197, 2023). "In addition to GSDMD, HsGSDME has been reported to be cleaved by both CASP3 and granzyme B at the same 267DMPD270 site, leading to the enhanced cytotoxicity of GSDME on cancer cells." (PMID 37134086, 2023). "Although the specific regulatory mechanism of GSDME and EGFR requires more study, our findings indicate that the GSDME-EGFR interaction may be a ubiquitous cancer-promoting factor." (PMID 37085908, 2023).
cancer (continued). "These cells have high levels of perforin and Granzyme B (Gzm B), and with the help of perforin, Gzm B can be delivered into cancer cells directly or indirectly, via coordinating with caspase-3, cleave the identical amino acid site D270 of the N-terminal domain of GSDME, activating pyroptosis." (PMID 37208730, 2023). "Therapies that targeting cancer cells with high GSDME expression are speculated to show a promising therapeutic effect." (PMID 36209102, 2022). "We conclude that reactivating GSDME expression and thereby inducing cancer cell-specific pyroptosis could be a potential therapeutic strategy against GC." (PMID 35517821, 2022). "Interestingly, GSDME, in turn, enable us to enhance the intrinsic apoptotic pathway in cancer cells by forming pores in the mitochondria with GSDME-N and liberating proapoptotic factors (including Cyt c and HtrA2)." (PMID 36457716, 2022). "GSDME is highly expressed in most normal tissues and weakly expressed in some malignant tumors." (PMID 35856558, 2022). "GSDME is an epigenetically silenced tumor suppressor gene in most cancer cells." (PMID 36387211, 2022). "GSDMB, GSDMC, GSDMD, GZMB, and GSDME displayed extensive CNV amplification across cancer types." (PMID 35620284, 2022). "Since VEGF promoted cancer angiogenesis and metastasis, we suspected that GSDME might be involved in CRC growth and metastasis via VEGF related pathways in CRC." (PMID 35164740, 2022). "GSDME is silenced in most cancer cells but is expressed in many normal tissues." (PMID 36091790, 2022). "Hence, we suspected that GSDME was positively correlated with the production of VEGF by cancer cell." (PMID 35164740, 2022). "The pyroptosis induced by the cleavage of GSDME is the main form of cancer cell death." (PMID 35462927, 2022). "As proved, GSDME is lowly expressed in most cancer cells, so we can suppose that with reversal of GSDME expression level, pyroptotic therapy may exert an important role in cancer treatment." (PMID 36209102, 2022). "GSDME was shown to be underexpressed in four cancer types and overexpressed in seven others." (PMID 35922531, 2022). "Gasdermines (GSDMD, GSDMA, GSDMB, and GSDME) showed hypermethylation across cancers." (PMID 36605187, 2022). "In addition to GSDMD, another gasdermin protein family member (GSDME) can be cleaved by activated caspase-3, and N-terminal-cleaved GSDME can also lead to pyroptosis of cancer cells." (PMID 36428598, 2022). "GSDME reportedly exerts positive effects on immunity in cancer." (PMID 36119049, 2022). "In addition, several small-molecule inhibitors targeting KRAS, EGFR, and ALK in lung cancer also stimulate cancer cell pyroptosis through the caspase-3/GSDME pathway." (PMID 35856558, 2022). "This might partly be explained by the caspase-3/GSDME signal pathway, which could shift the balance between apoptosis and pyroptosis in cancer." (PMID 36177050, 2022). "The discovery of the role of GSDME in various diseases reflects the fact that GSDME-targeted therapy might be an effective pattern for the treatments of various diseases, especially cancers." (PMID 35462927, 2022). "However, in this study, we found that only the expression levels of GSDME, caspase‐8, and caspase‐3 were significantly correlated, whereas the expression of caspase‐9 was low in most cancer tissues." (PMID 34553845, 2022). "However, further research is required to elucidate the exact role of GSDME and its related proteins in cancer." (PMID 34553845, 2022). "We speculate that this situation can explain the abnormal phenomenon in KIRC: patients with high expression of pyroptosis can produce a large number of GSDME proteins in cancer cells and drill holes in many biofilms in cells." (PMID 35795559, 2022).